ALB (albumin)
Diseases named in the same sentence as ALB in open-access papers (continued):
Sharing a sentence is not in itself a finding about the gene and the disease.
Sepsis (continued). "The CRP/albumin-ratio (CAR) has already been investigated as an outcome predictor in various diseases, like sepsis, cancer, cardiovascular diseases, stroke, and intracerebral hemorrhage." (PMID 38791046, 2024). "Second, wediscovered that the lactate/albumin ratio can be usedto predict mortality and MODS in sepsis patients,implying that the lactate/albumin ratio can beemployed in clinical practice to refine the risk stratifistratificationof sepsis patients further." (PMID 39139159, 2024). "Our analyses revealed significant genetic correlations between BUN, creatinine, urine albumin, UACR, kidney stones, and sepsis." (PMID 39086896, 2024). "In literature, various studies that had used SOFA score for the assessment of severity of sepsis, have supported these findings of the current study about the key parameters of the SOFA score system, SOFA score, and serum albumin levels." (PMID 39539863, 2024). "Logistic regression analysis showed that serum Mrp 8/14, albumin and APACHE II were the independent factors for predicting the prognosis of sepsis-induced ARDS during ICU hospitalization after adjustment." (PMID 39686985, 2024). "The neutrophil-albumin ratio (NAR), platelet-lymphocyte ratio (PLR), and C-reactive protein (CRP)-albumin ratio (CAR) are other promising biomarkers for use in patients with cancer, sepsis, and heart failure." (PMID 38222994, 2024). "The negative correlation coefficient means that with the decrease in serum albumin level, the SOFA score goes up (sepsis severity increases)." (PMID 39539863, 2024). "The nomogram development in this study incorporated six predictive factors, namely weight, sepsis, chronic heart failure, SOFA score, white blood cell count, albumin." (PMID 37884898, 2023). "The lactate/albumin ratio (LAR) has been used as a novel prognostic indicator for aneurysmal subarachnoid hemorrhage, traumatic brain injury, sepsis, heart failure, and acute respiratory failure." (PMID 37900597, 2023). "A study of patients with sepsis revealed that ACAG had the most significant prognostic validity for in-hospital mortality of ICU patients with sepsis, outperforming albumin and AG." (PMID 37118662, 2023). "A comparison of sepsis markers was done on the basis of CRP levels, N:L ratio, procalcitonin levels, and serum albumin levels." (PMID 38058329, 2023). "Albumin’s established role in cirrhosis, effectively managing complications like LVP, AKI, HRS-AKI, and SBP, contrasts with its emerging but complex role in sepsis, where treatment is complicated by the disease’s heterogeneity." (PMID 38139434, 2023). "With this in mind, albumin infusion should be highly considered due to its beneficial effects on ARDS and possibly toward sepsis." (PMID 36909040, 2023). "We performed an ROC curve analysis on four indicators, namely, FAR, ferritin, albumin, and SOFA score, to predict the 28-day mortality rate in sepsis patients." (PMID 37817258, 2023). "Biochemical analysis and white blood cell count depicted that sepsis-affected neonates had increased PCT, CRP, ALT, and neutrophil count and lowered levels of ALB, lymphocyte count, and LCR." (PMID 37197571, 2023). "However, a post hoc analysis suggested that albumin might reduce death odds in severe sepsis cases." (PMID 38139434, 2023). "The included albumin level data were also those assessed before DIC diagnosis, ranging from a point in time before sepsis diagnosis up to the point of sepsis diagnosis." (PMID 36362708, 2022). "First, sepsis and AF are related to inflammatory diseases, leading to increased RDW elevation and decreased albumin levels." (PMID 36494633, 2022). "ROC curve analysis showed that CAR had a higher discriminatory power than CRP, ALB, and PCT in predicting sepsis in neonates with pneumonia." (PMID 35873709, 2022).
Sepsis (continued). "LPS administration significantly elevated the levels of AST, ALT, and DBIL, and decreased the ratio of ALB to GLB compared to the normal controls, which indicated liver dysfunction in the sepsis group." (PMID 35345558, 2022). "The primary purpose of this study was to determine whether ambulation ability with albumin as a measure of nutritional status and C-reactive protein as an indicator of response to sepsis are predictive of 28-day mortality in elderly patients diagnosed with sepsis." (PMID 35962331, 2022). "Our study aimed to evaluate the clinical features of patients admitted to the tertiary intensive care unit with the diagnosis of sepsis and evaluate the effect of the SOFA score, prealbumin, albumin, and other laboratory parameters on hospital mortality." (PMID 36465747, 2022). "We found that hemoglobin, Na+, andbilirubin were highly significant indicating their role in severe sepsis, while nosignificant changes were shown with the MCV, MCH, MCHC, RBS, serum K+,SGOT, SGPT, ALP and albumin/globulin ratio." (PMID 35141523, 2022). "Patients in the low baseline albumin concentration group were older, more likely to be admitted to the ICU after surgery, more likely to have severe sepsis or acute respiratory distress syndrome, and less likely to have had TBI." (PMID 36430652, 2022). "The possible mechanisms of the high BAR and poor prognosis of sepsis can be explained in terms of BUN and albumin levels." (PMID 36407534, 2022). "To further evaluate the predictive value of RAR, RAW, albumin, SOFA score, SAPS II score, and RAR combined with different scoring systems in patients with sepsis for 28-day mortality, we constructed receiver operating characteristic (ROC) curves." (PMID 36211519, 2022). "In our study, the ALB level was identified as a significant and independent prognostic factor for death at 28 days and 90 days after CRRT initiation among sepsis patients with AKI undergoing CRRT." (PMID 35109818, 2022). "This study aimed to investigate the relationship between the blood urea nitrogen to serum albumin ratio (BAR) and in-hospital mortality in patients with sepsis." (PMID 36407534, 2022). "In the univariate analysis, several variables were significantly correlated with sepsis: the presence of HCC, MELD score, CTP score, Child–Pugh B and C cirrhosis, more than 1 L of ascites, HH, serum platelet count, albumin, bilirubin level, and PT." (PMID 35139804, 2022). "Previous studies have shown that lactate/albumin ratio (LAR) can be used as a better prognostic biomarker and can independently predict the mortality of critically ill patients, such as sepsis and severe heart failure." (PMID 34407102, 2021). "The median CRP in those with sepsis was 121mg/dl and CRP/Albumin among septic patient was found to be 3.4." (PMID 35199783, 2021). "Basal albumin leak was found to be significantly lower in human pulmonary MECs (HPMEC) than in HUVECs, but septicemia increases the leak across both types." (PMID 33725263, 2021). "The Scr, Albumin, WBC, CRP and PCT levels in sepsis patients were significantly different from those in healthy controls (P < 0.001)." (PMID 34376255, 2021). "Overall, 126 out of 186 patients (67.7%) in this study were administered albumin for an appropriate indication as defined by our criteria utilizing the FDA-labeled indications, Surviving Sepsis Campaign guidelines, and the study by Buckley and colleagues." (PMID 34613990, 2021). "Glycocalyx damage is associated with changes plasma protein concentration, particularly HSA and blockage of albumin transport can produce the systemic symptoms seen in SARS-CoV-2 infection and sepsis." (PMID 33088822, 2020). "After completing a logistic regression analysis, white blood cell (WBC), anemia, procalcitonin (PCT), C-reactive protein (CRP), albumin, and alanine transaminase (ALT) demonstrated a significant difference in differentiating KD from sepsis." (PMID 32792679, 2020).
Sepsis (continued). "Our NMA also has some limitations: first, in sepsis trials (sample size [n] = 14,659), the evidence was adequate between balanced crystalloids and saline, L-HES, and albumin, but insufficient between balanced crystalloids and gelatin." (PMID 33317590, 2020). "In the present review, it was observed that the mean or median serum albumin levels of patients with AKI were much lower than normal values, which was attributed to sepsis and accompanying systemic inflammation." (PMID 32933198, 2020). "Serum biochemical analysis showed that the levels of PCT, ALT, UREA, and UA were significantly higher in neonates with sepsis (P < 0.05), while serum TBIL, TP, and ALB levels were lower (P < 0.001)." (PMID 33344658, 2020). "Univariate regression analysis results indicate significant correlation to PIICS development by all of the following: age, male sex, SOFA and APACHEII score, sepsis, initial CRP, albumin, lymphocyte count, Hb and creatinine on admission." (PMID 32824569, 2020). "On the other hand, albumin is used in cirrhosis for the treatment of SBP and was widely discussed in the sepsis treatment for its immunomodulatory and anti-inflammatory properties." (PMID 32576140, 2020). "Our network meta-analysis found that balanced crystalloids and albumin decreased mortality more than L-HES and saline in sepsis patients; however, saline or L-HES was better than iso-oncotic albumin or balanced crystalloids in traumatic brain injury patients." (PMID 33317590, 2020). "After obtaining these cell-specific conditional TNFR1−/− mice using Villin-, Tie2-, or albumin cre lines, respectively, we subjected them to the CLP-induced sepsis model and compared their response with that of the TNFR1flox/flox control mice." (PMID 31787972, 2019). "There was a statistically significant relationship between severe sepsis with TPE and inotropic drug use, albumin use, RBC transfusion, mortality, blood calcium, ALT, AST, LDH, uric acid, haemoglobin, and platelet count." (PMID 31284692, 2019). "SOFA score, serum albumin level, hemoglobin level, and diagnosis at the time of starting CRRT (such as sepsis or severe infectious diseases, heart failure, and after cardiac surgery) were also analyzed." (PMID 31827924, 2019). "Considering that the patients with sepsis usually had higher values of inflammatory markers such as CRP or procalcitonin, CRP/ALB ratio in these patients would have higher ratio than with other studies including our study." (PMID 29495423, 2018). "Patients with severe sepsis symptoms display metabolic dysfunction with elevated levels of plasma NEFA and lower levels of albumin." (PMID 29760707, 2018). "The C-reactive protein/albumin ratio (CRP/Alb), consisting of CRP and albumin, was initially used to assess the outcome of patients with acute medical admissions and sepsis." (PMID 28431566, 2017). "Instead, fluid resuscitation in sepsis as defined by the SSC includes initial fluid challenge with crystalloids as the first choice of fluid (grade 1B), followed by albumin as the second choice if patients are unresponsive to large amounts of crystalloids." (PMID 27313844, 2016). "Patients who had sepsis had a higher NRS-2002 score and chromium levels and lower albumin and thiamine levels." (PMID 26938553, 2016). "Considering all clinic and laboratory parameters in multiple logistic regression analysis, low serum albumin and high NRS-2002 scores had the greatest accuracy in predicting death, SIRS and sepsis in patients admitted to the infectious disease clinic." (PMID 26938553, 2016). "Our study demonstrated that an initial serum albumin <3.5 g/dL and an ED triage diastolic blood pressure <52 mmHg had independent, statistically significant associations with early future progression to severe sepsis or shock among patients with nonsevere sepsis." (PMID 26908009, 2016).
Sepsis (continued). "In this context, risk factors predictive of PRF include type of surgery, emergency status, dependent functional status, preoperative sepsis, higher American Society of Anesthesiologists (ASA) class, acute kidney injury, and low albumin." (PMID 27980860, 2016). "Pulmonary microvascular Evans blue (EB)-labeled albumin leak increased by 2 h and peaked 4 h after CLP-induced sepsis, in parallel to and directly correlated with significant septic PMVEC death in vivo, as well as, and specifically, apoptosis." (PMID 26376777, 2015). "Following CLP-sepsis, the time-dependent disruption of pulmonary microvascular/PMVEC barrier function, as reflected by pulmonary microvascular EB-albumin permeability in vivo, was strongly correlated (r = 0.976, p < 0.05) with IVVM PMVEC death (PI+)." (PMID 26376777, 2015). "These trials are RASP (NCT01337934) evaluating use of LR compared to 4% albumin in patients with early sepsis, PRECISE (NCT00819416) looking at 5% albumin versus NS in early septic shock, and EARRS (NCT00327704) comparing NS to 20% albumin." (PMID 25625012, 2014). "In critically ill patients, particularly those with sepsis, the relationship between COP and the albumin concentration is complex, being influenced by altered permeability and increased transcapillary escape rates." (PMID 25042164, 2014). "On the other hand, higher cystatin C level was an independent predictor of mortality in the ICU, when adjusted by age, gender, APACHE II score, vasopressors, sepsis, ICU hospitalization days, and serum albumin level." (PMID 24967238, 2013). "In sepsis and leptospirosis, high plasma levels of NEFA and low albumin concentrations are correlated to the disease severity." (PMID 22529526, 2012). "Other than one surgery trial, all six other included trials of hyperoncotic albumin involved cirrhotic patients, whereas those evaluating hyperoncotic HES all concerned surgery or sepsis." (PMID 21029460, 2010). "Hyperoncotic albumin displays protective effects on the kidney and hence would likely offer a safer fluid management alternative than HES in sepsis." (PMID 18318896, 2008). "Additional covariates related to fluid status or protein binding, such as bilirubin, albumin, total protein, mechanical ventilation, and sepsis, were evaluated but did not significantly improve the model." (PMID 41288085, 2026). "Subgroup analyses indicated a stronger association in patients without severe AKI, CKD, sepsis or CRRT, and patients with lower levels of age or Acute Physiology Score (APS) III and higher levels of albumin (p < 0.05 for all)." (PMID 42090376, 2026). "Albumin-corrected anion gap (ACAG) has been proposed to overcome this limitation, yet its prognostic value in patients with sepsis complicated by heart failure (HF) remains unclear." (PMID 41630251, 2026). "Until now the net leakage of albumin has not been evaluated in patients with sepsis nor has it been correlated to the total fluid overload, markers of inflammation and glycocalyx damage." (PMID 40057738, 2025). "In sepsis, ARF, and combined sepsis and ARF cases, initial LAR was a better predictor of in-hospital outcomes such as in-hospital mortality, need for inotropes, and mechanical ventilation than albumin alone, and SOFA scores." (PMID 40130722, 2025). "AUC value with 95% CI, sensitivity and specificity of lactate/albumin ratio, lactate alone and SOFA score for predicting in hospital outcomes such as mortality, need of inotropes and requirement of mechanical ventilation among sepsis cases." (PMID 40130722, 2025). "The 2021 guidelines concluded that albumin is not the preferred fluid for resuscitation in patients with sepsis or septic shock and recommended against the use of gelatin and starch for sepsis resuscitation." (PMID 40600034, 2025). "Given this previous evidence, we thus expect no average effect of albumin on mortality in sepsis patients." (PMID 39899627, 2025).
Sepsis (continued). "However, in recent years, strong evidence has reinforced the role of the SIC score, serum albumin levels, and the TPRI in assessing sepsis severity." (PMID 40710030, 2025). "In this study, albumin levels were significantly lower in non-survivors compared to survivors, reinforcing its potential role as a prognostic marker in sepsis." (PMID 40310418, 2025). "For instance, the multicenter Saline versus Albumin Fluid Evaluation (SAFE) trial found no significant adverse effects of albumin on renal function in sepsis." (PMID 40841985, 2025). "None of the markers i.e. LAR, lactate alone, SOFA score and Albumin level were effective at predicting the duration of hospital stay among cases of ARF or combined sepsis and ARF regardless of in hospital outcome." (PMID 40130722, 2025). "Mass balance calculations, considering lymphatic return, have been used to assess net albumin leakage (NAL) in major surgery but not in sepsis." (PMID 40057738, 2025). "Notably, their study also found that RAR had superior predictive value for sepsis incidence and 28-day mortality compared to RDW or albumin alone." (PMID 40964688, 2025). "Serum albumin and the SIC score, indirect indicators of capillary leaks and sepsis-induced coagulopathy, respectively, have been extensively but independently studied as short-term mortality predictors in sepsis." (PMID 40648856, 2025). "The variables that were insignificant as a result of the model (BUN, albumin, lung disease, oliguria (first day), diuretic use, RRT used, and sepsis) were removed, and the general model was established with the significant variables BAR, vasopressor requirement, and mechanical ventilation." (PMID 40731862, 2025). "Despite the importance of serum albumin as a prognostic indicator for sepsis, incorporating serum creatinine and examining the ACR value provide a methodologically superior approach in prognostic studies, as serum albumin level is often confounded by renal function." (PMID 40978746, 2025). "The lactate/albumin ratio(LAR), an easy-to-calculate marker, has been found to correlate with the development of multiple organ dysfunction syndrome, as well as predict ICU and in-hospital mortality and long-term mortality in sepsis and septic shock." (PMID 40130722, 2025). "Regarding laboratory tests, parameters including N%, IG%, Hb, ALB, TBIL, K, P, Ca, Cr, Cysc, CRP, IgA, APTT, PT, D-dimer, Fib, Lac, PLT, and PCT in the sepsis group were significantly different from those in the non-sepsis group (P < 0.05)." (PMID 40933706, 2025). "Blood urea nitrogen to albumin ratio (BAR) has served as a predictive marker for patients in the Intensive Care Unit (ICU), and has been studied in patients with sepsis, post-cardiac surgery, severe COVID-19, and acute exacerbation of chronic obstructive pulmonary disease (AECOPD)." (PMID 40373080, 2025). "Except for specific indications (e.g., in patients with cirrhosis, sepsis resuscitation after initial volume therapy with BC), albumin should not be used." (PMID 39382683, 2024). "The relationship between blood urea nitrogen to albumin ratio (BAR) and the prognosis of patients with tuberculosis (TB) complicated by sepsis remains unclear." (PMID 39013924, 2024). "The albumin level, indicative of poor prognosis in sepsis, is also absent from both scoring systems." (PMID 39767798, 2024). "These factors included albumin at ICU admission, the duration of deep sedation before MRC scoring, RFCSA atrophy rate between D1 and D3, average norepinephrine dosage, length of ICU stay before MRC scoring, and the occurrence of sepsis." (PMID 39033122, 2024). "For sepsis, the participants with ACR 3–30 mg/mmol and > 30 mg/mmol had HRs of 1.53 (95% CI 1.24–1.90) and 3.14 (95% CI 1.94–5.1), respectively, compared to normal albumin excretion." (PMID 38679665, 2024). "Despite no clear benefit of human serum albumin on mortality in non-selected patients with septic shock, albumin still represents a potential treatment in sepsis." (PMID 38326920, 2024).